CXCL10 (C-X-C motif chemokine ligand 10)
Diseases named in the same sentence as CXCL10 in open-access papers (continued):
Sharing a sentence is not in itself a finding about the gene and the disease.
immunotoxicity (1 paper, 2018). "Results from the sparse PLS models selecting both exposures and proteins suggest a swimming-induced immunotoxicity through decreased level of IL-8, VEGF, CCL22, CCL11, CRP and CXCL10, and increased levels of IL-1ra, which antagonises the proinflammatory IL-1." (PMID 29563153, 2018).
intrahepatic cholestasis (1 paper, 2024). A cholestasis characterized by impairment of the bile flow caused by obstruction located in the liver. "Patients with BA have significantly higher levels of CXCL10 at the time of HPE procedure when compared with both a disease control, intrahepatic cholestasis (IHC) and normal controls." (PMID 38860860, 2024).
kidney injury (1 paper, 2024). Trauma to the kidney. "Propofol has been demonstrated to inhibit TNF-α, IL-6, and CXCL-10 expression in I/R-induced kidney injury." (PMID 39054453, 2024).
lentivirus infection (1 paper, 2024). Virus diseases caused by the Lentivirus genus. "By implicating chemokines like CXCL10 as hubs of putatively pathogenic inflammatory networks in Lentivirus infection, we hypothesize that pharmacological targeting of these pathways could represent a novel strategy to modulate lentiviral virulence in HIV." (PMID 38317183, 2024). "Further, we identify CXCL10 and CXCL16 as important molecular drivers of inflammatory pathways specifically in response to highly pathogenic Lentivirus infection." (PMID 38317183, 2024).
male infertility (1 paper, 2017). The inability of the male to effect fertilization of an ovum after a specified period of unprotected intercourse. "The CXCL10/CXCR3 system in testicular cells might be considered as a therapeutic target for male infertility caused by MuV infection." (PMID 29072682, 2017).
mastocytoma (1 paper, 2024). A localized tumor composed of sheets of mast cells without atypia. "Inspired by these studies on their potential beneficial effects in anti-tumor therapy, we genetically engineered murine mastocytoma line P815 with light-switchable modules (named P815-IFNG) to produce murine IFNG and CXCL10." (PMID 39080467, 2024).
meningioma (1 paper, 2023). A generally slow growing tumor attached to the dura mater. "Moreover, Meningiomas could cause lower levels of interleukin-16 and higher levels of CXCL10 in the blood." (PMID 37425011, 2023). "Meningiomas also affect the expression of cytokines such as IL-16 and CXCL10." (PMID 37425011, 2023).
meningococcal infection (1 paper, 2025). Infections with bacteria of the species neisseria meningitidis. "Despite strain and donor variability, meningococcal infection universally induced cytokines CCL20, CXCL1, CXCL8, CXCL10, and IL-18, with significantly higher CCL20 levels 24 h post-MenW cc11 infection." (PMID 40586572, 2025). "Upon meningococcal infection, we observed a mostly universal induction of CCL20, CXCL1, CXCL8, CXCL10, and IL-18 secretion 24 h post-infection, regardless of the specific meningococcal strain used for infection." (PMID 40586572, 2025).
metastatic colorectal cancer (1 paper, 2023). "Recently our group demonstrated that higher levels of IL-6 and CXCL10 were significantly associated with poor disease-free survival in metastatic colorectal cancer (mCRC) patients treated with bevacizumab plus oxaliplatin-based regimens." (PMID 36902351, 2023).
mood disorder (1 paper, 2024). A cognitive disorder a disturbance in which the person's mood is hypothesized to be the main underlying feature. "The limitation of using a complex, partially characterized stimulant like LPSCM is that factors which may not be relevant to mood disorders, such as LPS, higher levels of chemokines like CXCL9 and CXCL10, could have also influenced the glial cells significantly." (PMID 39539342, 2024).
mucosa-associated lymphoid tissue lymphomas (1 paper, 2024). "This response may be accompanied by IL-8, IL-2, CXCL-9 and CXCL-10 to the site of inflammation, with excess immune overstimulation by persistent antigens creating B-lymphocyte hyperplasia, triggered by T-cells, which can lead to mucosa-associated lymphoid tissue lymphomas." (PMID 39608222, 2024).
multinodular goiter (1 paper, 2021). Nodular goiter characterized by more than one discrete tissue mass. "A study showed that circulating CXCL9 and CXCL10 levels were significantly elevated in patients with AIT compared with normal controls or patients with multinodular goiter." (PMID 34868029, 2021).
muscular dystrophy (1 paper, 2023). Muscular dystrophy (MD) refers to a group of more than 30 genetic diseases characterized by progressive weakness and degeneration of the skeletal muscles that control movement. "From our own research, the following scheme can be proposed: low end CK and high end GDF-15 and CXCL10 levels point toward IBM, high end CK and intermediate GDF-15 and CXCL10 levels point toward IMNM, and high end CK and low end GDF-15 and CXCL10 point toward a muscular dystrophy." (PMID 37007787, 2023).
necrotizing fasciitis (1 paper, 2015). "When analyzing tissue biopsies from patients with necrotizing fasciitis caused by Streptococcus pyogenes, extracellular histone H4 and CXCL10 are immunostained in necrotic, but not healthy tissue." (PMID 26646682, 2015).
neurotoxicity (1 paper, 2025). Toxicity that causes injury to the central or peripheral nervous system or damages its function. "Neurotoxicity is a pathological phenomenon seen in neuroHIV that was also observed through transfer of cell-free CM from Ephb2 activated microglia onto neurons, which our data suggest is a consequence of the assortment of pro-inflammatory secreted factors (IL-6, CXCL10, TNFα, IL-1β etc.)." (PMID 40588746, 2025).
Nocardia infection (1 paper, 2022). "Further experiments indicated that Nocardia infection could activate microglia and drive M1 microglial polarization, promote iNOS and CXCL-10 production, and cause neuroinflammation in the substantia nigra, all of which may be involved in causing PD-like symptoms." (PMID 36352407, 2022). "Therefore, we detected the expression of markers of M1 (iNOS, CXCL-10, and CD86) and M2 (CD206 and ARG1) microglia after Nocardia infection using BV2 cells." (PMID 36352407, 2022).
ocular sarcoidosis (1 paper, 2016). A leading cause of inflammatory eye disease is sarcoidosis. "Serum levels of CXCL9 and CXCL10 have been correlated with serum ACE levels in presumed ocular sarcoidosis." (PMID 26879979, 2016).
of the CNS (1 paper, 2022). "Other chemokines are considered exploratory biomarkers in MS: Results of several studies demonstrate that CXCL9 and CXCL10 (also called interferon-γ-inducible protein 10, IP-10) are secreted in various diseases of the CNS, especially in neuroinflammation." (PMID 36142860, 2022).
organizing pneumonia (1 paper, 2019). "CXCL10, a pro-inflammatory cytokine that is a CXCR3 ligand, has been previously found to be associated with diffuse alveolar damage in and development of CLAD and also as a risk factor for CLAD development in the context of organizing pneumonia post-transplantation." (PMID 30781765, 2019). "A total of 60 BAL samples (20 with bronchiolitis obliterans (BOS), 20 with restrictive allograft syndrome (RAS), and 20 with stable allografts (STA)) were collected from 60 unique lung transplant patients; cfDNA and CXCL10 were measured by the ELISA-based KIT assay." (PMID 30781765, 2019).
osteonecrosis (1 paper, 2023). A none disease characterized by death of bone tissue due to a lack of blood supply. "Furthermore, SARS-CoV-2 infection causes an increase in inflammatory cytokines such as C-X-C motif–chemokine 10 (CXCL10), interferon gamma (IFN-γ), interleukins (ILs) 1 beta, 6, 8 and 17, and tumor necrosis factor alpha (TNF-α), resulting in bone mineral loss, osteonecrosis and chondrolysis." (PMID 36984576, 2023).
otitis media (1 paper, 2024). Inflammation of the anatomical structures of the middle ear, which is most often caused by an infectious process. "The role of CXCL10 in otitis media has hardly been investigated so far." (PMID 38541021, 2024).
ovarian serous cystadenocarcinoma (1 paper, 2022). A malignant serous cystic epithelial neoplasm arising from the ovary. "Positive correlations were found between the mRNA levels of BCL3 with some of these target genes, such as TNFAIP3/A20, CCL2, CD274, and CXCL10, in brain lower grade glioma (LGG) and ovarian serous cystadenocarcinoma (OV) samples from TCGA database." (PMID 35990614, 2022).
papilloma (1 paper, 2020). A benign epithelial neoplasm that projects above the surrounding epithelial surface and consists of villous or arborescent outgrowths of fibrovascular stroma. "We found a novel regulator, stress keratin 17 (K17), was induced in expression following MmuPV1 infection, and that K17 was critical for preventing T cell infiltration in MmuPV1-induced papillomas by inhibiting the CXCL9/CXCL10/CXCR3 axis." (PMID 31968015, 2020). "There were decreases in both infiltrating CD4 and CD8 T cells in the papillomas arising in K17KO blocked with anti-CXCR3, suggesting the increased infiltration of CD8+ T cells in K17KO mouse papillomas was mediated by the CXCL9/CXCL10/CXCR3 signaling axis." (PMID 31968015, 2020). "We also confirmed upregulated expression of IFNγ-related genes by RT-qPCR, including IFNγ, PD-L1, CXCL9 and CXCL10 in K17KO papillomas." (PMID 31968015, 2020). "In the K17KO papillomas, while we found significant induction of CXCL9 and CXCL10, there was a significant reduction in CXCL11 RNA level compared to WT papillomas (p = 0.0002)." (PMID 31968015, 2020). "Cellular genes involved in immune response were differentially expressed in the papillomas arising on the K17KO mice correlating with increased numbers of infiltrating CD8+ T cells and upregulation of IFNγ-related genes, including CXCL9 and CXCL10, prior to complete regression." (PMID 31968015, 2020).
pemphigus (1 paper, 2021). Pemphigus is a group of rare autoimmune diseases that cause blistering of the skin and mucous membranes (mouth, nose, throat, eyes, and genitals).This conditioncan occur at any age, but often strikes people in middle or older age. "CXCL10 was expressed throughout the epidermis and has been implicated in the pathogenesis of human pemphigus." (PMID 34660634, 2021). "CXCL8 and CXCL10 mediate recruitment of leukocytes to the skin from the blood, and have been implicated in the pathogenesis of human pemphigus." (PMID 34660634, 2021). "Direct comparison of our dataset to previously published human pemphigus datasets revealed five conserved differentially expressed genes: CD19, WIF1, CXCL10, CD86, and S100A12." (PMID 34660634, 2021).
Peptic ulcer (1 paper, 2013). The term peptic ulcer refers to acid peptic injury of the digestive tract, resulting in mucosal break reaching the submucosa. "Statistical comparison of serum CXCL10 concentration between peptic ulcer (PU) and asymptomatic (AS) groups according to the anti-CagA status." (PMID 23467184, 2013). "Comparison of the serum CXCL10 levels in patients with peptic ulcer (PU), asymptomatic (AS) and control groups." (PMID 23467184, 2013). "Comparison of the serum CXCL10 levels in peptic ulcer (PU), asymptomatic (AS) and control groups according to gender." (PMID 23467184, 2013).
peripheral nerve injury (1 paper, 2020). Injury to a peripheral nerve. "Our present findings further this line of research by elucidating the potential mechanistic role of CXCL10/CXCR3 signaling in the development of neuropathic pain following peripheral nerve injury." (PMID 32265928, 2020).
PFAPA syndrome (1 paper, 2010). An auto inflammatory syndrome characterized by recurrent febrile episodes associated with aphthous stomatitis, pharyngitis and cervical adenitis. "Elevated levels of the IFNγ-induced chemokines CXCL9/MIG and CXCL10/IP10 in the absence of Th2- and Th17-associated cytokines indicated that components of a Th1-type inflammatory response coincide with fever in PFAPA syndrome." (PMID 20819226, 2010).
pituitary tumour (1 paper, 2020). "We also observed a negative correlation between microvessel density and the levels of CXCL10 and CX3CL1 released by pituitary tumour cells." (PMID 32946040, 2020).
polyarteritis nodosa (1 paper, 2021). Polyarteritis nodosa (PAN) is a rare, clinically heterogeneous, rheumatologic disease characterized by necrotizing inflammatory lesions affecting small- and medium-sized blood vessels. "However, some hints of a potential role of JAK/STAT may come from the evidence of an upregulation of STAT3 in the PB CD4+ and CD8+ T cells of polyarteritis nodosa (PAN) patients and of increased levels of CXCL10 (a STAT induced gene) in active Kawasaki disease." (PMID 33854436, 2021).
posterior uveitis (1 paper, 2025). Inflammation of the choroid as well as the retina and vitreous body. "Posterior uveitis-induced retinal inflammation caused by LPS is reduced by lipoxins by virtue of their ability to inhibit CXCL9 (MIG) and CXCL10 (IP10), which are ligands for the CXCR3 chemokine receptor." (PMID 40005295, 2025).
Premature ovarian insufficiency (1 paper, 2023). Amenorrhea due to loss of ovarian function before the age of 40. "CXCL10 which is a small signaling protein involved in immune response and inflammation may have diagnostic potential in detection of premature ovarian insufficiency." (PMID 38107572, 2023).
pressure ulcers (1 paper, 2021). "For the Δ2bp carriers in mild SCI, our data suggested that these individuals were at higher risk of pressure ulcers and were associated with higher circulating levels of IFN-γ, CXCL10, and CCL4 but lower circulating levels of IL-12p70." (PMID 33956875, 2021). "In mild SCI, the risk of pressure ulcers was associated with circulating levels of IFN-γ, IL-12p70, CXCL10, and CCL4, and the associations were influenced by the Δ2bp variant." (PMID 33956875, 2021). "For the mild SCI Δ2bp carriers, risk of pressure ulcers was positively associated with circulating levels of IFN-γ, CXCL10, and CCL4 and negatively associated with circulating levels of IL-12p70." (PMID 33956875, 2021). "Thus, for the Δ2bp carriers in mild SCI, a higher risk of pressure ulcers was associated with higher circulating levels of IFN-γ, CXCL10, and CCL4 and lower circulating level of IL-12p70." (PMID 33956875, 2021).
progeria (1 paper, 2026). "We further characterized CXCL10, which has not previously been associated with progeria in mice or humans." (PMID 41959364, 2026).
psychosis (1 paper, 2022). "Overall, we found that four factors (CD30, BAFF, CCL20, and CXCL10) might be associated with treatment of psychosis." (PMID 35618730, 2022). "In all the psychosis patients combined, CD30, BAFF, CCL20, CXCL10, and IFN-γ R1 achieved enough power (>80%)." (PMID 35618730, 2022).
pulpitis (1 paper, 2022). Inflammation of the dental pulp. "Moreover, we have shown that HDPCs stimulated with Pam3CSK4, known as the TLR2 ligand, could produce C-X-C motif chemokine ligand 10 (CXCL10) which is a member of the CXC chemokine family and play an important role in the progression of pulpitis." (PMID 36421669, 2022).
Pyoderma (1 paper, 2024). Any manifestation of a skin disease associated with the production of pus. "We found CXCL10, a gene associated with inflammatory responses, to be highly upregulated in many CID conditions including CCLE, MLE, and pyoderma." (PMID 39911479, 2024).
radiation pneumonitis (1 paper, 2023). Inflammation of the lung due to harmful effects of ionizing or non-ionizing radiation. "The activation of the CXCL10/CXCR3 axis exacerbated radiation pneumonitis by inducing excessive autophagy, thereby hindering NK cells from clearing damaged tissue cells and hyper-reactive inflammatory cells." (PMID 38077388, 2023). "Our study revealed that CXCL10/CXCR3 activation in radiation pneumonitis leads to increased NK cell infiltration, while the accumulation of reactive oxygen species (ROS) causes excessive autophagy, thereby inhibiting NK cell function." (PMID 38077388, 2023). "ELISA results reveal a significant increase in CXCL10 levels in the peripheral blood supernatant of patients who developed radiation pneumonitis." (PMID 38077388, 2023). "Given that CXCL10 displayed significant changes in both groups, we hypothesized that CXCL10 may play an important role in radiation pneumonitis." (PMID 38077388, 2023).
Respiratory insufficiency (1 paper, 2024). "During the 30-day follow-up, symptoms improved, and a decrease was recorded in levels of CXCL10, which has been associated with greater viral load, respiratory insufficiency, pulmonary lesions, and mortality in SARS-CoV-2 infection." (PMID 38360855, 2024).
salivary gland tumors (1 paper, 2025). "In patients with salivary gland tumors (WT and PA), various chemokines have been determined, including CCL28, CXCL10, CXCL12, CCL18, and CXCL1, as well as pro-inflammatory cytokines such as IL-1β, IL-6, IL-4, IL-17, and IL-33." (PMID 40807046, 2025).
Salmonella Infections (1 paper, 2024). Infections with bacteria of the genus SALMONELLA. "(C–E) RT-qPCR analysis of mRNAs encoding inflammatory cytokines (Tnfα, Il1β, and Il6), chemokines (Ccr2, Ccl2, Cxcl1, and Cxcl10) and macrophage biomarkers (Nos2 and Arg1) in BMDMs measured at the indicated times after Salmonella infection (multiplicity of infection [MOI] = 1) (n = 5)." (PMID 39475776, 2024).
secretory otitis media (1 paper, 2024). "It has recently been shown, in secretory otitis media (SOM), that different inflammatory mediators, such as CXCL1, IL-16, IL-8, IL-17, IL-1β, CXCL10, and CXCL9, were found in high concentrations in middle ear fluids, in association with the presence of bacterial and viral nucleic acid levels." (PMID 38541021, 2024).
seminoma (1 paper, 2025). A radiosensitive malignant germ cell tumor found in the testis (especially undescended), and extragonadal sites (anterior mediastinum and pineal gland). "Taken together, we unveiled the functionally discrete roles of IL-6 and TNFα in shaping the pro-inflammatory TME in seminomas, although we cannot exclude the possibility that tumor cells produce additional soluble factors like the chemokines CXCL10 that are involved in this process." (PMID 40649953, 2025).
septic arthritis (1 paper, 2006). "The mean level of synovial CXCL10 in the autoimmune arthritis patients was comparable with that measured in septic arthritis." (PMID 16846531, 2006).
Shock (1 paper, 2014). The state in which profound and widespread reduction of effective tissue perfusion leads first to reversible, and then if prolonged, to irreversible cellular injury. "CXCL10 was present at high concentrations in plasma and peritoneal cavity during CLP-induced septic shock." (PMID 24890566, 2014).
skin Paget disease (1 paper, 2023). "In skin Paget disease, the cells release soluble RANKL, improving the secretion of CCL5, CCL17, and CXCL10 from RANK+ M2 polarized TAMs, suggesting that Paget cells can modulate the microenvironment landscape by the stimulation of TAMs." (PMID 37958292, 2023).
skin squamous cell carcinoma (1 paper, 2022). A carcinoma arising from the squamous cells of the epidermis. "In skin squamous cell carcinomas, upregulation of ETV1 was sufficient to induce most CAF effectors upregulated by fibroblast growth factor (FGF), which could promote the secretion of multiple chemokines with macrophage-recruiting activity including CXCL1, CXCL10, and CXCL11." (PMID 35860243, 2022).
spirochete infection (1 paper, 2022). "Stimulation of human microglia by LPS or IFNβ produced during spirochete infection results in enhanced transcription of CXCL10 and microglia-derived CXCL10 secretion 79-82." (PMID 36483597, 2022).
staphylococcus aureus pneumonia (1 paper, 2023). An pneumonia caused by infection with Staphylococcus aureus. "Likewise, the chemokines CXCL9 and CXCL10 had the best sensitivity, specificity, and predictive power to differentiate between S. pneumoniae and Staphylococcus aureus pneumonia." (PMID 37893128, 2023).